LINC00460 (long independently transcribed non-coding RNA 460)
Gene: Long non-coding RNA gene on chromosome 13 (106,374,477 to 106,384,315, forward strand). Ensembl gene ENSG00000233532.
Diseases named in the same sentence as LINC00460 in open-access papers:
LINC00460 is named in the same sentence as 45 diseases in open-access papers, as found by Europe PMC text mining. Sharing a sentence is not in itself a finding about the gene and the disease. The quoted sentences say what the papers report.
colorectal cancer (22 papers, 2019 to 2024). A primary or metastatic malignant neoplasm that affects the colon or rectum. "LINC00460 has been reported in various tumors such as head and neck squamous cell carcinoma, cervical cancer, bladder cancer, colorectal cancer, and is implicated in tumor proliferation, migration, mesenchymal transition, drug resistance, and increased tumor progression." (PMID 36992704, 2023). "Indeed, elevated LINC00460 amounts were significantly associated with poor OS in bladder cancer, cervical cancer, colorectal cancer, esophageal cancer, gastric cancer, HNSCC, liver cancer, lung cancer, osteosarcoma, pancreatic cancer and papillary thyroid carcinoma." (PMID 35906593, 2022). "LINC00460/DHX9/IGF2BP2 complex stimulates colorectal cancer proliferation and metastasis by interacting with IGF2BP2 and regulating HMGA1 mRNA stability by m6A modification." (PMID 37744330, 2023). "Recent studies have shown that LINC00460 is overexpressed in multiple cancers and plays an important role in tumour progression, including that in head and neck squamous cell carcinoma, colorectal cancer, osteosarcoma, and hepatocellular carcinoma." (PMID 36513874, 2023). "Some previous studies have suggested that LINC00460 primarily affects cell invasion and migration in such cancers as esophageal cancers, epithelial ovarian cancer, colorectal cancer and gastric cancer." (PMID 31429766, 2019). "In addition, upregulation of LINC00460 was also associated with poor progression free survival (PFS) in AML, colorectal cancer, gastric cancer, glioma, hepatocellular carcinoma and lung adenocarcinoma and osteosarcoma." (PMID 35906593, 2022). "Similarly, LINC00460, which contributes to radioresistance in colorectal cancer, is activated by c-Jun." (PMID 34834139, 2021). "Furthermore, a great deal of research has identified that LINC00460 plays an important role in gastric cancer, papillary thyroid carcinoma, colorectal cancer, and other malignant tumors." (PMID 32775417, 2020). "It has been validated that LINC00460 functions as a competing endogenous RNA (ceRNA) in co-expression and promotes the malignant development of multiple cancers, including prostate cancer, skin cancer, hepatocellular cancer, colorectal cancer and so on, except for RCC." (PMID 36387102, 2022). "In addition, LINC00460 is significantly upregulated in colorectal cancer." (PMID 34803512, 2021). "This confirms the potential of LINRIS-IGF2BP2-MYC axis for colorectal cancer targeted therapy; LncRNA LINC00460 interacts with IGF2BP2 and DHX9 to form the LINC00460/DHX9/IGF2BP2 complex." (PMID 35070987, 2021). "Moreover, LINC00460 was found to interact with IGF2BP2 in promoting the proliferation and metastasis of colorectal cancer by increasing the stability of HMGA1 mRNA via an m6A-mediated modification." (PMID 36438499, 2022). "LINC00460 is positively correlated with advanced TNM stages and lymph node metastasis in papillary thyroid carcinoma and with invasion depth and TNM stage in colorectal cancer." (PMID 31429766, 2019).
lung cancer (17 papers, 2018 to 2025). A malignant neoplasm involving the lung. "LINC00942, LINC01116, SNHG4, MIR31HG, and LINC00460 had been known to be associated with tumor development and progression and drug resistance in various cancers including lung cancer." (PMID 35083132, 2021). "This may help to develop novel therapeutic strategies for the prevention and treatment of metastatic tumors from cigarette smoke-caused lung cancer by blocking the nicotine-activated LINC00460 pathway." (PMID 31123168, 2019). "LINC00460 promotes cell migration and invasion in lung cancer by inducing epithelial-mesenchymal transition (EMT) in cancer cells." (PMID 40302795, 2025). "LINC00518 and LINC00460 act as oncogenes to facilitate tumor progression, including prostate cancer, gastric cancer, colon cancer, and lung cancer." (PMID 33042838, 2020). "In lung cancer, elevated linc00460 binds with and translocates hnRNPK to the cytoplasm to participate in special mRNA stability and translation regulation, and also plays a key role in cell migration and invasion." (PMID 30658384, 2019). "In the present study, we determined that LINC00460 was overexpressed in lung cancer tissues, which led to a poor prognosis in patients with NSCLC." (PMID 31123168, 2019). "It has been reported that LINC00460 induces EMT in lung cancer cells." (PMID 31429766, 2019). "Furthermore, hnRNPK is known to interact with linc00460 to promote lung cancer cell metastasis." (PMID 31110205, 2019). "Furthermore, a recent study has shown that LINC00460 is up-regulated in several cancers, including pancreatic cancer, breast cancer, lung cancer, colon cancer and bladder cancer, indicating that LINC00460 may play an important role in PAAD." (PMID 29849937, 2018). "Studies have revealed that LINC00460 is significantly upregulated in NSCLC and promotes the metastasis and invasion of lung cancer cells by inducing epithelial–mesenchymal transformation." (PMID 36291859, 2022). "LINC00460 expression is a potential marker for aggressive phenotypes in distinct tumors, including HPV-negative HNSC, stage IV KIRC, locally advanced lung cancer and basal-like BRCA." (PMID 33912452, 2021). "One study reported that LINC00460 interacts with hnRNPK to promote EMT and cell migration in lung cancer cells." (PMID 31429766, 2019). "Linc00460 binds with and translocates hnRNPK that is located in nucleus to the cytoplasm to participate in special mRNA stability and translation regulation, and promotes cell migration and invasion through inducing EMT in lung cancer formation." (PMID 35505438, 2022). "Linc00460 binds with and translocates hnRNPK that is located in nucleus to the cytoplasm to participate in special mRNA stability and translation regulation, and promotes cell migration and invasion through inducing EMT in lung cancer." (PMID 35505438, 2022).
gastric cancer (11 papers, 2019 to 2024). A primary or metastatic malignant neoplasm involving the stomach. "LINC00460 acts as an oncogene in breast cancer and gastric cancer, and its high expression is correlated with unfavorable outcomes in patients with breast cancer." (PMID 36060239, 2022). "Recent studies showed that some non-coding RNAs, such as Linc00483, Linc00460, and Linc01436, adsorbed miR-30a-3p and weakened the tumor-suppressive effects in gastric cancer, nasopharyngeal carcinoma, and non-small cell lung cancer, respectively." (PMID 32899691, 2020). "Additionally, LINC00460 was shown to be upregulated in gastric cancer and was correlated with dismal patient prognoses." (PMID 38850527, 2024). "Additionally, previous study also demonstrated marked increase of LINC00460 level in gastric cancer tissues and cell lines and the promoting effect of LINC00460 on the proliferation, migration and invasion of gastric cancer cells, which can be partly reversed by LINC00460 downregulation." (PMID 33345740, 2021).
pancreatic cancer (11 papers, 2017 to 2025). "For instance, LINC00460 is reported to play an important role in pancreatic cancer by regulating immune cell infiltration." (PMID 40308809, 2025). "Downregulation of UBE2V1 significantly inhibits the proliferation and metastasis of pancreatic cancer, while overexpression of LINC00460 can partially reverse the inhibitory effect of UBE2V1." (PMID 37786443, 2023). "Inhibition of LINC00460 attenuated pancreatic cancer cell proliferation and metastasis, whereas its overexpression reversed this effect." (PMID 37786443, 2023). "Overall, these results indicated that under hypoxic conditions, HIF-1α induced upregulation of linc00460 in pancreatic cancer, and that this required the HRE1 binding site in the promoter of LINC00460." (PMID 37786443, 2023). "Overall, we found that hypoxia-induced LINC00460 plays a role of oncogene in pancreatic cancer, and upregulation of LINC00460 is closely related to tumor proliferation, metastasis, and poor prognosis." (PMID 37786443, 2023). "We determined that LINC00460 has higher expression in pancreatic cancer tissues than in normal tissues, in both TCGA database and using data from our institute." (PMID 37786443, 2023). "Overall, these results indicated that LINC00460 is an oncogene and potential therapeutic target for pancreatic cancer." (PMID 37786443, 2023). "More interestingly, overexpression of LINC00460 partially reversed this inhibitory effect in pancreatic cancer cell lines." (PMID 37786443, 2023). "For instance, downregulation of LINC00460 inhibited the growth and promoted the apoptosis of pancreatic cancer cells, showing potential as a novel biomarker and promising therapeutic strategy for pancreatic cancer." (PMID 35996496, 2022). "LINC00460 expression is tightly correlated with tumor size in patients with several cancers such as osteosarcoma, and breast, colorectal, liver and pancreatic cancers." (PMID 35906593, 2022). "The role of LINC00460 as an oncogene was also reported in hepatocellular carcinoma, pancreatic cancer, kidney malignancy, and prostate cancer." (PMID 36060239, 2022). "Significantly increased LINC00460 level was reported in pancreatic cancer (PC) patients as compared to the healthy controls, indicating that LINC00460 has the potential to be used as an effective biomarker of prognosis and diagnosis of PC." (PMID 33345740, 2021). "In summary, our study elucidated that downregulation of LINC00460 inhibited the proliferation, migration and invasion, and promoted the apoptosis of pancreatic cancer cells via modulation of miR-320b/ARF1 axis." (PMID 33345740, 2021). "CCK-8 and colony formation assays indicated that down-regulation of UBE2V1 reduced the proliferation ability of pancreatic cancer cell lines, while overexpression of LINC00460 could partly rescue this effect." (PMID 37786443, 2023). "To investigate whether upregulation of LINC00460 was induced by hypoxia, we exposed pancreatic cancer cell lines to hypoxia and normoxia conditions for 24 and 48 h or treated with CoCl2 for 48 h." (PMID 37786443, 2023). "Thus, we demonstrated that the role of LINC00460 in pancreatic cancer is achieved by regulating its downstream molecules, miR-4689, and further mediates the expression of UBE2V1." (PMID 37786443, 2023). "Finally, compared with normal pancreatic epithelial cells, LINC00460 expression increased in seven of the eight pancreatic cancer cell lines tested." (PMID 37786443, 2023). "Moreover, LINC00460 knockdown inhibited the proliferation, migration and invasion, as well as promoting the apoptosis of pancreatic cancer cells." (PMID 33345740, 2021).
pancreatic cancer (continued). "Furthermore, we identified that LINC00460 was upregulated in other tumors and may be a latent oncogene in pancreatic cancer." (PMID 37786443, 2023). "Nevertheless, the specific role of LINC00460 in pancreatic cancer remains unclear." (PMID 37786443, 2023). "Therefore, we speculated that LINC00460 might also function as a ceRNA in pancreatic cancer." (PMID 37786443, 2023). "Mechanistically, LINC00460 plays the role of oncogene by acting as a sponge of miR-4689, activating its downstream target, UBE2V1, and sequestering USP10 to promote the proliferation and metastasis of pancreatic cancer." (PMID 37786443, 2023). "Along with six other top DEGs, i.e. TINAG, LINC00460, UGT1A9, SLCO1B7, HOTTIP, and ALCO1B3, their expression status could not be found in the Pancreatic Cancer Database." (PMID 28418924, 2017).
breast carcinoma (6 papers, 2018 to 2024). "LINC00460 was observed to be significantly elevated in doxorubicin-resistant breast cancer cells, and LINC00460, together with FUS, promotes MYC expression by influencing the efficiency of intron removal during mRNA maturation." (PMID 39372872, 2024). "They found that LINC00460 is upregulated in breast cancer and its overexpression promotes cell viability, migration, and invasion both in vitro and in vivo." (PMID 38491511, 2024). "Further to this, high levels of Linc00460 are correlated with shorter overall survival in breast cancer patients while its silencing prevented tumor growth in in vivo experiments and attenuated the malignant progression of breast cancer cells." (PMID 36139687, 2022). "We found that LINC00460 is overexpressed in five different epithelial cancers, namely: Breast cancer (BRCA); Colon adenocarcinoma (COAD); Head and Neck Squamous cell carcinoma (HNSC), Pancreatic adenocarcinoma (PAAD) and Rectum adenocarcinoma (READ) (Log2FC>1; p<0.05)." (PMID 33912452, 2021). "Conversely, LINC00460 transcription is directly activated by c-MYC and forms a positive feedback loop in breast cancer cells, driving resistance to tamoxifen." (PMID 39372872, 2024).
head and neck squamous cell carcinoma (6 papers, 2020 to 2023). A squamous cell carcinoma that arises from any of the following anatomic sites: lip and oral cavity, nasal cavity, paranasal sinuses, pharynx, larynx, and salivary glands. "Most recently, several studies have shown LINC00460 was overexpressed in multiple cancers, such as gastric cancer, lung cancer, head and neck squamous cell carcinoma (HNSCC), hepatocellular carcinoma and colon cancer." (PMID 33526059, 2021).
lymph node metastasis (6 papers, 2017 to 2022). "Another study found that the expression of LINC00460 is independently associated with the OS in terms of the lymph node metastasis and Tumor Node Metastasis (TNM) stages." (PMID 36588797, 2022). "Our study showed that the expression of LINC00460 was associated with lymph node metastasis and pathological differentiation, which is consistent with the results of esophageal cancer." (PMID 31429766, 2019). "Statistical analysis suggested that linc00460 high-expressiongroup presented more lymph node metastasis and later TNM stage than linc00460low-expression group." (PMID 28939763, 2017). "LINC00460 expression was positively correlated with esophageal squamous cell carcinoma TNM stage and lymph node metastasis and predicted poor prognosis." (PMID 32775417, 2020). "The expression of LINC00460 in LSCC with lymph node metastasis had no significant changes when compared with that without of lymph node metastasis (p > 0.05)." (PMID 31336999, 2019).
colon cancer (5 papers, 2018 to 2024). "The results showed that LINC00460 was mainly localized in the cytoplasm of colon cancer cells." (PMID 33526059, 2021). "Knockdown of LINC00460 promote colon cancer cell invasion and migration in vitro." (PMID 31632435, 2019). "Knockdown of LINC00460 promotes colon cancer cell invasion and migration in vitro." (PMID 31632435, 2019). "We assessed the expression levels of CASC19 and LINC00460 genes in a pool of colon cell lines: DLD-1, COLO-205, HCT116, and LoVo as colon cancer models and CCD841 as a normal epithelial cell line." (PMID 38740871, 2024). "Three colon cancer cells (SW620, HCT116, and LOVO) were treated with 5‐aza‐2′‐deoxycytidine for 48 h, and the LINC00460 expression was observed." (PMID 31632435, 2019).
esophageal squamous cell carcinoma (5 papers, 2018 to 2021). Esophageal squamous cell carcinoma (ESCC) is a type of esophageal carcinoma (EC) that can affect any part of the esophagus, but is usually located in the upper or middle third. "Experiments found that LINC00460 depletion suppressed cell growth in esophageal squamous cell carcinoma through regulating cell proliferation and the cell cycle and accelerated cell apoptosis in esophageal squamous cell carcinoma." (PMID 32775417, 2020). "Another study reported that elevated expression of LINC00460 is associated with advanced clinical stages, lymph node metastasis, and a poor prognosis in esophageal squamous cell carcinoma (ESCC), and that LINC00460 knockdown induces cell cycle arrest and apoptosis in ESCC cells." (PMID 30069008, 2018). "In esophageal squamous cell carcinoma (ESCC), cAMP-response element binding protein binding protein (CBP) and EP300 up-regulates the expression of LINC00460 through binding to the promoter of LINC00460 and regulating its chromatin architecture." (PMID 34094983, 2021).
lung adenocarcinoma (5 papers, 2019 to 2023). A carcinoma that arises from the lung and is characterized by the presence of malignant glandular epithelial cells. "In summary, we established and validated lncRNA prognostic models associated with angiogenesis in lung adenocarcinoma and determined the prognostic value of LINC00857, RBPMS-AS1, SYNPR-AS1 and LINC00460 in LUAD." (PMID 36999053, 2023). "First, we learned from the data of GEPIA that LINC00460 was overexpressed in lung adenocarcinoma tissues compared with the normal tissues (*P<0.05)." (PMID 31123168, 2019). "In addition, the expression of LINC00460 is increased in several cancers, such as lung adenocarcinoma, and nasopharyngeal carcinoma." (PMID 35915466, 2022).
prostate carcinoma (5 papers, 2020 to 2023). A carcinoma that arises from epithelial cells of the prostate gland. "It has been confirmed that LINC00460 functioned as an oncogene regulating prostate cancer progression through the promotion of cell proliferation and a reduction in apoptosis." (PMID 37251440, 2023). "Previous study suggested that LINC00460 level exhibits high expression in human prostate cancer tissues and cell lines, and downregulation of LINC00460 suppresses cell proliferation and promotes cell apoptosis in prostate cancer, which is consistent with our study." (PMID 33345740, 2021).